SLC28A2 (solute carrier family 28 member 2)
Description:
Sodium-dependent and purine-selective transporter. Exhibits the transport characteristics of the nucleoside transport system cif or N1 subtype (N1/cif) (selective for purine nucleosides and uridine). Plays a critical role in specific uptake and salvage of purine nucleosides in kidney and other tissues. May contribute to regulate the transport of organic compounds in testes across the blood-testis-barrier (Probable).
Synonyms: hCNT2; CNT2; SPNT1; HsT17153
Tractability: Small molecule: a high-quality ligand is known. Antibody: UniProt places it where antibodies can reach, with high confidence; its Gene Ontology location is reachable by antibodies, with high confidence; UniProt predicts a signal peptide or a membrane-spanning region. PROTAC: ubiquitination databases record sites on it; a small molecule that binds it is known.
Target class: Transporter; SLC28 Na+-coupled nucleoside transport family; Electrochemical transporter; SLC28 and SLC29 families of nucleoside transporters; SLC superfamily of solute carriers
Safety:
Unwanted effects reported when the protein is acted on. In parentheses: how it was acted on, where the effect was seen, and who reports it.
anemia (source: ClinPGx)
hematologic toxicity (source: ClinPGx)
nephrotoxicity (source: ClinPGx)
survival time (source: ClinPGx)
Gene: Protein-coding gene on chromosome 15 (45,252,234 to 45,277,846, forward strand). Ensembl gene ENSG00000137860.
Subcellular location: Membrane; Apicolateral cell membrane
Subcellular location (Human Protein Atlas): Vesicles
Pathways (Reactome):
Drug ADME: Azathioprine ADME; Ribavirin ADME
Transport of small molecules: Transport of nucleosides and free purine and pyrimidine bases across the plasma membrane
Gene Ontology:
Molecular function: neurotransmitter transmembrane transporter activity; nucleoside:sodium symporter activity; purine nucleobase transmembrane transporter activity; purine nucleoside transmembrane transporter activity; pyrimidine- and adenosine-specific:sodium symporter activity; uridine transmembrane transporter activity; azole transmembrane transporter activity; nucleoside transmembrane transporter activity
Biological process: adenosine transport; inosine transport; neurotransmitter transport; nucleoside transmembrane transport; purine nucleobase transmembrane transport; purine nucleoside transmembrane transport; pyrimidine-containing compound transmembrane transport; uridine transmembrane transport; azole transmembrane transport; nucleobase-containing compound metabolic process; retina homeostasis; transport across blood-brain barrier; xenobiotic metabolic process; xenobiotic transmembrane transport; pyrimidine nucleobase transport
Cellular component: apicolateral plasma membrane; brush border membrane; coated vesicle; membrane; plasma membrane; vesicle membrane
Genetic constraint (gnomAD): Loss-of-function variants: 44 observed, 48.05 expected, observed/expected ratio (o/e) 0.92, 90% interval 0.72 to 1.18. The upper end of that interval is the gene's LOEUF score, 1.18, which puts it in group 5 of 6, group 1 being the genes least tolerant of losing a copy. Missense variants: 561 observed, 620.3 expected, observed/expected ratio (o/e) 0.9, 90% interval 0.84 to 0.97. Synonymous variants: 237 observed, 239.22 expected, observed/expected ratio (o/e) 0.99, 90% interval 0.89 to 1.1.
Homologues: Orthologues: chimpanzee SLC28A2 (99% identical), macaque SLC28A2 (95% identical), pig SLC28A2 (85% identical), rabbit SLC28A2 (85% identical), rat Slc28a2 (81% identical), rat LOC120101643 (80% identical), mouse Slc28a2 (80% identical), guinea pig SLC28A2 (78% identical), mouse Slc28a2b (76% identical), tropical clawed frog slc28a2 (57% identical), zebrafish slc28a1 (52% identical), rat LOC120101644 (36% identical), and 4 more. Paralogues in human: SLC28A1 (62% identical), SLC28A3 (43% identical).
Diseases named in the same sentence as SLC28A2 in open-access papers:
SLC28A2 is named in the same sentence as 18 diseases in open-access papers, as found by Europe PMC text mining. Sharing a sentence is not in itself a finding about the gene and the disease. The quoted sentences say what the papers report.
hyperuricemia (5 papers, 2017 to 2025). An abnormally high level of uric acid. "Hyperuricemia and gout are significantly correlated with genetic heritability and support the correlation with the SLC28A2 gene." (PMID 31360730, 2019).
colorectal cancer (4 papers, 2019 to 2025). A primary or metastatic malignant neoplasm that affects the colon or rectum. "A high SLC28A2 mRNA expression was found in lung, ovary, uterus and prostate cancers, while a low expression was detected in hepatocellular carcinoma, colorectal carcinoma, colorectal carcinoma liver metastases, as well as in kidney, stomach, rectum and small intestine cancers." (PMID 36839686, 2023).
gout (2 papers, 2019). A condition characterized by painful swelling of the joints, which is caused by deposition of urate crystals. "In this study, we identified intron SNPs (rs16941238 and rs2413769) significantly associated with both SUA level and HUA phenotype, and another exonic SNP (rs2271437) associated with gout in the SLC28A2 gene." (PMID 30679935, 2019). "Then, by performing a meta-analysis combining results obtained in the present study and that acquired from our previous GWAS, we attempt to further examine the relationship between the SLC28A2 gene and gout." (PMID 30679935, 2019). "In conclusion, we demonstrate the significant associations of intron variants in the SLC28A2 gene with both SUA level and HUA phenotype, and another exonic variant with gout." (PMID 30679935, 2019). "Our findings support the associations of the SLC28A2 gene with the SUA level, the HUA phenotype and gout in Han Chinese." (PMID 30679935, 2019). "The current study is designed to investigate relationships between SLC28A2 polymorphisms and SUA concentrations, HUA, as well as clinically ascertained gout in the Han Chinese population with additional sample sets." (PMID 30679935, 2019). "This study aims to identify whether a candidate gene, SLC28A2, exerts susceptibility for SUA fluctuation and incidence of HUA and gout in the Han Chinese population." (PMID 30679935, 2019).
leukemia (2 papers, 2016 to 2023). A malignant (clonal) hematologic disorder, involving hematopoietic stem cells and characterized by the presence of primitive or atypical myeloid or lymphoid cells in the bone marrow and the blood. "This was supported by increased AZA sensitivity of canine kidney and leukemia cell lines transfected with SLC28A1 compared to cells lines transfected with SLC29A1, SLC29A2, and SLC28A2." (PMID 36834962, 2023). "In line with the present findings, SLC28A1, SLC28A2, and SLC28A3 were poorly expressed in primary bone marrow blasts and leukemia cell lines." (PMID 36834962, 2023). "The mRNA amounts of the main nucleoside transporters (NT) and intracellular metabolizing enzymes (ME), hENT1, hENT2 (SLC29A2), hCNT1 (SLC28A1), hCNT2 (SLC28A2), hCNT3 (SLC28A3), DCK and cN-II (NT5C2), were measured in 50 pediatric leukemia cases by RQ-PCR." (PMID 27391351, 2016).
anemia (1 paper, 2016). A reduction in the number of red blood cells, the amount of hemoglobin, and/or the volume of packed red blood cells. "Therefore, currently ribavirin levels seem to be of little value to predict anemia, for which hopefully studies e.g. on polymorphisms in the inosine triphosphatase (ITPA) or the SLC28A2 genes will enable a more precise view in the future." (PMID 27388623, 2016).
Crohn disease (1 paper, 2020). A gastrointestinal disorder characterized by chronic inflammation involving all layers of the intestinal wall, noncaseating granulomas affecting the intestinal wall and regional lymph nodes, and transmural fibrosis. "Interestingly, the hCNT2-encoding gene (SLC28A2) is by far the most dramatically down-regulated one among the purinome-related genes in inflamed ileal mucosa samples from Crohn’s disease patients." (PMID 33233484, 2020).
Obesity (1 paper, 2021). Accumulation of substantial excess body fat. "Parental high-fat diet increased offspring obesity and type 2 diabetes mellitus risks through the regulation of SLC28A2 (solute carrier family 38 member 2) expression, which indicated that lncRNA-SLC28A2 may be associated with chicken lipid synthesis." (PMID 34249911, 2021).
tumor (2 papers, 2024). "SLC28A2, VIP, CMKLR1, MARCO, and NOD2 were detected at low levels in non-tumor and tumor cells." (PMID 38742117, 2024).
SLC28A2 also shares sentences with these, for which no sentence is quoted: Cerebral ischemia (1 paper); COVID-19 (1); gastric cancer (1); infection (1); ischemia (1); mucinous ovarian carcinoma (1); ovarian carcinoma (1); pancreatic tumours (1); rectal cancer (1); type 2 diabetes mellitus (1).